IL1A (interleukin 1 alpha)
Diseases named in the same sentence as IL1A in open-access papers (continued):
Sharing a sentence is not in itself a finding about the gene and the disease.
infection (continued). "In the event of intra-amniotic infection or choriodecidual space infection, inflammatory cytokines such as IL-1α, IL-1β, IL-6, IL-8, and granulocyte colony-stimulating factor are released." (PMID 23818902, 2013). "Starting at day 1 post infection, control animals also had higher levels of several cytokines, including IL-1α, IL-1β, IL-6, IL-12p70, and IFN-γ in plasma, additionally IL-17 and TNF-α and chemokines (KC, MCP-1, MIP-1α) were elevated in lungs." (PMID 22448290, 2012). "IL-1α, IL-1β, and the IL-1 receptor antagonistic molecule (IL-1 Ra) are expressed in the testis under normal homeostasis and they further increase upon infection/inflammation." (PMID 23251650, 2012). "Interleukin-1 is necessary for the control of infection with M. tuberculosis, but the role of its two ligands, IL-1α and IL-1β, and its regulation in vivo are poorly understood." (PMID 23251798, 2012). "The experiment of infection realized with the strain M. paratuberculosis 1515 and enteric glial cells showed a production of IL-1A and IL-6 already after 24 hours after the infection, until the achievement of a plateau after 48 hours." (PMID 22151930, 2011). "The experiment performed with the microglial cells confirmed the results obtained with the enteroglial cells after the infection with M. tuberculosis and M. bovis, whereas M. paratuberculosis stimulated the production of IL-1A and IL-1B." (PMID 22151930, 2011). "In a study it was observed that after the infection of microglial cells by M. tuberculosis, the production of cytokines IL-1A and IL-10 was prevented." (PMID 22151930, 2011). "IL-1α and IL-1β has been known to form an important part of the inflammatory response of the body against infection." (PMID 21345237, 2011). "The infection of enteric glial cells with M. tuberculosis H37Rv stimulated the production of IL-1A, TNF-α, G-CSF, GM-CSF and, to a lesser extent, of IL-1B." (PMID 22151930, 2011). "The infection of microglial cells with M. paratuberculosis stimulated the expression of IL-1A and IL-1B." (PMID 22151930, 2011). "Curiously, the role of IL-1A is to recruit leucocytes in the infection site and to take part, together with TNF-α, in the formation and the maintenance of the granuloma." (PMID 22151930, 2011). "Regarding the infection of microglial cells with M. tuberculosis and M. bovis, these microorganisms stimulated the production of IL-1A, IL-1B, TNF-α, G-CSF and GM-CSF; besides M. bovis stimulated the production also of IL-6." (PMID 22151930, 2011). "NHBE cells infected (MOI = 0.5) with TX/02 (H5N3) induced higher apical IL-1α expression and significantly more basolateral expression (p<0.05), evident at 24 h pi, compared to infection with the other AIV viruses or mock treatment." (PMID 21731666, 2011). "At this phase of infection before severity of disease, there was an increase in expression of various proinflammatory mediators also like Tnf-α, Il1α, Il1β, Il-12 and Ccl2/MIP-1α along with chemoattractants." (PMID 21371334, 2011). "The genes that were suggestive for association with PTB in fetal (IL1A, IL4 and MMP8) and maternal samples (IL-1R2 and IL-6R) in both the MoBa and Cenn studies were mainly infection and inflammation genes (sector D)." (PMID 20140262, 2010). "Proinflammatory cytokines CXCL8 and CXCL5 are chemoattractants for neutophils, IL-1α and IL-1β are important proinflammatory cytokines and would be expected to be increased early in infection." (PMID 22331987, 2010). "Pro-inflammatory members of the interleukin-1 (IL-1) family of cytokines (IL-1α and β) are important mediators of host defense responses to infection but can also exacerbate the damaging inflammation that contributes to major human diseases." (PMID 18939951, 2009).
infection (continued). "Upon skin injury, trauma, or infection, IL-1α is promptly released, reaching its peak in the first 12–24 h initiating local inflammation and facilitating the recruitment of neutrophils to the wound site, thereby removing debris and preventing bacterial infection." (PMID 40182989, 2025). "In contrast, in the absence of infection, sterile inflammatory signals called “alarmins” (i.e., IL-1α, HMGB1, S100A, etc.)are produced in the uterus, causing spontaneous preterm labour." (PMID 41227337, 2025). "Eight days post-infection, the animals were sacrified and vaginal washes were performed to quantify the pro-inflammatory cytokine IL-1α and the chemokine MIP-2 (functional equivalent in mouse of human IL-8) whose expression were shown to be strongly induced in response to Candidalysin." (PMID 41069059, 2025). "IL1A is a member of the cytokine family, which acts as a mediator of the immune response, while CXCL8 encodes for a member of a chemokine family, acting as a chemotactic factor by guiding the neutrophils to the site of infection (data from NCBI)." (PMID 39858269, 2025). "IL-1α and IL-1β are known to induce an inflammatory response and acute immune response, including the proliferation and recruitment of macrophages and neutrophils to the infection site." (PMID 38533263, 2024). "In contrast, blockade of IL-1α (aIL-1a mice) significantly reduced weight loss with no change in food intake after infection." (PMID 38382577, 2024). "Of note, we detected IL-1α in the brain after either infection or nasal delivery." (PMID 38382577, 2024). "However, the observed variations in CRP and IL-1α levels during the early phase of infection highlight the dynamic changes in inflammatory responses that occurred during the course of the disease." (PMID 39338474, 2024). "Therefore, hTert-RPE 1 cells were incubated with interleukin 1α (IL-1α) before infection to induce a more pro-inflammatory cell type." (PMID 38731826, 2024). "Conversely, the wildtype mice had a dramatic rise in serum IL-1α following infection." (PMID 38594380, 2024). "The levels of pro-inflammatory cytokines such as IL-1α, IL-1β, IL-2, IL-6, IL-12, IL-17, INFγ, and TNFα increased in the serum of mice infected with fungal strains from a very early stage (3 h) to 7 days post infection." (PMID 38783167, 2024). "Also, infection with SARS-CoV-2 induced IL-1α expression and release, however this process was evident 3 days after infection." (PMID 38664396, 2024). "Despite increased viral load, infection-associated weight loss was significantly reduced after IL-1α (but not IL-1β) blockade." (PMID 38382577, 2024). "A model of infection wherein non-immune, Chlamydia-infected epithelial cells recruit immune cells into affected tissues is uniquely persuasive, given epithelial cells secrete a host of pro-inflammatory cytokines (e.g. IL-1α, IL-8, GROα, GM-CSF) in both murine and in vitro models of infection." (PMID 37265500, 2023). "IL-1α and IL-1β are released in the early stages of infection." (PMID 37112697, 2023). "Expression of genes within the periapical lesion after 14 days of infection was confirmed with real time PCR, where nociceptor-ablation resulted in a significant upregulation of IL1a (p = 0.01), Tnf (p = 0.01), and Nlrp3 (p < 0.01), whereas ablated mice had reduced expression of Alox5 (p = 0.03)." (PMID 37845223, 2023). "This assay showed similar results, in which IL-1α levels were significantly increased in dual-infected mice compared to S. maltophilia only infection (**P<0.01), and IL-1β levels showed a trending increasing in dual-infected mice compared to S. maltophilia infection." (PMID 36748431, 2023). "IL-1α recruit neutrophils to the infection site while IL-1β is a pro-inflammatory cytokine." (PMID 37756264, 2023).
infection (continued). "In response to infection, four interleukins (IL1A, IL1B, IL8 and IL16), their receptors (IL1 receptor like 1, IL1 receptor 2, IFN-lambda receptor 1, cytokine receptor like factor 1) and two acute phase proteins (Serum amyloid A 1 and 2) were differentially expressed." (PMID 38179419, 2023). "The IL-1α responses did, however, peak at 7 days post-infection." (PMID 37724291, 2023). "Indeed, we observed a significant decrease in TNF-licensed cell death early during infection, as well as significant attenuation of both IL-1α and IL-1β release, in Casp11-/- BMDMs relative to wild-type controls." (PMID 37279255, 2023). "Enhanced TNF and IL-1α levels were detected in septal macrophages early post infection." (PMID 37112697, 2023). "As is well known, IL-1α is an alarmin released by dying cells, as Rickettsia infected endothelial cells are, to initiate the early phase of sterile inflammation, while IL-1β is produced by inflammasomes at sites of tissue infection or sterile injury." (PMID 36551320, 2022). "Our assays revealed that Casp-11 was involved in the secretion of cleaved IL-1α upon infection of BMDMs with nonpathogenic and pathogenic Rickettsia spp." (PMID 35130729, 2022). "Importantly, infection of macrophage cultures with Af293 germlings was sufficient to induce equivalent damage and IL-1α release as with CEA10 germlings, which suggests that this was a morphotype-specific host response, absent with conidia." (PMID 35330266, 2022). "The interleukin-1 (IL-1) family members IL-1α and IL-1β, which are also proinflammatory cytokines, are produced by macrophages, DCs, and neutrophils during Mtb infection and are important in the early defense against infection." (PMID 36365041, 2022). "As our findings indicate that infections with R. typhi and R. rickettsii resulted in a significant reduction of IL-1α secretion, likely via a Casp-11-dependent mechanism, we assessed the expression and activation status of Casp-1 and Casp-11 via Western blot analyses." (PMID 35130729, 2022). "Furthermore, NAIP-/- and NLRC4-/- THP-1s treated with MCC950 secreted negligible levels of IL-1α, IL-1β, and IL-18, similar to those observed during ΔsipB Stm infection." (PMID 35073381, 2022). "In this effort, BMDMs derived from WT, Casp-1−/−, Casp-11−/−, and Casp-1/11−/− mice were infected with R. typhi, R. rickettsii, and R. montanensis, and the levels of IL-1β and IL-1α and cell death, as well as bacterial burdens, were evaluated over the course of infection." (PMID 35130729, 2022). "Importantly, this in turn correlated with significantly higher inflammation as determined by pro-inflammatory cytokine levels (CXCL1, IL-1α, IL-1β, IL-6 and G-CSF) in lung homogenate 3 days post infection (dpi)." (PMID 35330266, 2022). "Infection of Il-1β−/− or Il-1α−/− BMDMs with Rickettsia spp." (PMID 35130729, 2022). "After infected with Yersinia pseudotuberculosis, the highest infection-induced immunomodulatory genes were those of the major proinflammatory cytokines: interleukin-1 alpha (il1a), interleukin-1 beta (il1b), interleukin-6 (il6), interleukin-17F (il17f) and interferon gamma (ifng)." (PMID 36059501, 2022). "Furthermore, under sertaconazole nitrate treatment the IL‐1α liberation by infected skin models declined to control levels, indicating an effective control of infection." (PMID 35212482, 2022). "released significantly lower levels of IL-1β and IL-1α than infection of WT BMDMs." (PMID 35130729, 2022). "During NiV infection, epithelial cells and type II pneumocytes from the bronchiole are the primary targets and infection induces the production of inflammatory cytokines such as IL-6, IL-8, IL-1α and granulocyte-colony stimulating factor (G-CSF), responsible for the recruitment of immune cells." (PMID 35632678, 2022).
infection (continued). "Additionally, ASFV-Δ9L/Δ7R infection exhibited dramatic induction of genes important during the acute-phase response, such as IL-1A, IL-1B, IL-10, and IL-18, tumor necrosis factor alpha (TNF-α), and several members of the complement pathway (C1R)." (PMID 35867564, 2022). "We found that many cytokines messenger RNAs (mRNAs), including Il1b, Il5, Il6, Il10, Il12a/Il12p70, Ifng, Ccl4, Ccl5, Tnfa, Gcsf, Cxcl1, Il1a, and Il3, were significantly induced upon B.1.351 infection in the lungs of hACE2 transgenic, BALB/c, and C57BL/6 mice." (PMID 34907154, 2021). "However, it is not clear which immune mediators recruited neutrophils given that the neutrophil chemoattractants tested (KC, MIP-2 and IL-1α) were downregulated at 24h and 72h post infection with L. biflexa." (PMID 34249775, 2021). "In response to IL-1α, IL-1β, and IL-36 stimulation, keratinocytes express and release a host of antimicrobial peptides including human beta defensins, LL-37, and S100 proteins which directly combat infection." (PMID 35003136, 2021). "Similarly, infection of BMDM with the Mtb Δami4 mutant resulted in significantly increased production of IL-1α, IL-6, and IL-12p40." (PMID 33980132, 2021). "To clarify whether 2-methylpentane was a result of infection with Up or IL-1α induced inflammation, we compared all samples of Up induced CA with samples of IL-1α induced CA (Upalln = 6; IL-1α n = 19)." (PMID 34368028, 2021). "Inflammatory cells infiltrate the sites of infection at an early stage of the infection with SARS-CoV2 and cause a stormy release of pro-inflammatory cytokines like IL-6, IL-17A, TNFα, IFNγ, IL-1α/β, and chemokines like CC-chemokine ligand 2 (CCL2) as well as CXC-chemokine ligand 10 (CXCL10)." (PMID 33643316, 2021). "IL-1α synthesis can be induced by cell stress, injury, infection and proinflammatory mediators." (PMID 34449702, 2021). "Consequently, disruption of AS-IL1α function can limit IL-1α transcription and reduce the harmful effects of excessive IL-1α levels during infection and inflammatory disease." (PMID 33572313, 2021). "However, an enhanced upregulation of 9 genes, all involved in the NF-kB pathway (CCL2/MCP1, CCL20, CCL4, CXCL2/MIP2α, IL1A, NFKBIA, PTX3, TNFA, TNFAIP3), was observed after infection with D26 variants, in comparison to the WT." (PMID 33399033, 2021). "IL-1α−/− mice exhibited a significantly higher burden throughout GT infection." (PMID 34526512, 2021). "For that purpose, we verified whether BMDMs deficient in components of the pathway were able to release IL-1β, IL-1α, and IL-18 in the same manner as WT cells in response to the infection by live tachyzoites." (PMID 32523898, 2020). "Similar responses were observed following 48 h of infection, with significant associations between IL-8 and IL-1α and necrotic events in non-CF and CF AEC." (PMID 32328066, 2020). "Additionally, the respiratory epithelium upon the infection with hMPV can secrete IL-1α, IL-11, and IL-32." (PMID 32545470, 2020). "To investigate whether IL-1α can impact on the innate immunity against bacterial infection, we firstly built the in vivo model of E. coli infected rats and the infection on co-culture system of neutrophils and endothelial cells in vitro." (PMID 32733891, 2020). "IL-1β has been implicated in some infection models, but IL-1α activity in brain infection has not previously been reported." (PMID 32703941, 2020). "Moreover, several other cytokines, namely IL-12, IFN-γ, MCP-1, and IL-1α, which are critical to innate and acquired immunity, were rapidly up-regulated at day 2 PI after infection." (PMID 32316659, 2020). "A more focused investigation of infection-specific markers IL-1α, IL-1β, IL-6, IL-8, MCP-1, MIP-1α, and MIP-1β could provide insight into the power of these cytokines to discriminate aseptic vs. septic tissues." (PMID 32867801, 2020).
infection (continued). "The co-localization of tissue factor (TF) (a thrombin activator) and pro-IL-1α in the epidermis means that following injury thrombin generated during hemostasis can rapidly activate IL-1α, leading to inflammation and recruitment of immune cells that can safeguard against potential infection." (PMID 33391283, 2020). "However, our data point to a major role for IL-1α in shaping antifungal Th17 immunity, which boosts IL-17 production to regulate neutrophil recruitment into sites of infection." (PMID 31425553, 2019). "Interestingly, they also observed an increased release of IL-1α and IL-1β pro-inflammatory cytokines from cells at the infection sites in neutrophil-depleted mice, one week post-infection." (PMID 31847221, 2019). "Thus, IL-1α promotes Th17 cell survival during infection, which is essential for the host immune defense against fungi." (PMID 31425553, 2019). "In contrast to the IL1 receptor antagonist (IL1ra, anakinra), canakinumab acting selectively on IL1B but not on IL1A did not affect the host defences and susceptibility to the infection to such a large extent." (PMID 31780867, 2019). "Strikingly, 100% of Il1a-/- animals succumbed to infection, in contrast to 30% of WT mice." (PMID 31425553, 2019). "Importantly, IL-1α boosts the Th17 response in vivo, promoting adequate neutrophil recruitment into the lung, which reduces fungal burden and confers resistance to the infection." (PMID 31425553, 2019). "Keratinocytes also secreted p33 that could be processed by thrombin, suggesting thrombin cleavage of epidermal IL-1α after wounding could be an elegant mechanism to rapidly alert the immune system and safeguard against infection." (PMID 30926232, 2019). "Importantly, infection of Casp11-/- mice with P. brasiliensis recapitulated all aspects of the Th17 response observed in the lung of Il1a-/- animals at 30dpi." (PMID 31425553, 2019). "Given that IL-1α and IL-1β production kinetics were similar and that both cell types responded similarly, subsequent experiments were only performed for IL-1β using bmDCs following 16 h of infection." (PMID 31262357, 2019). "A robust innate immune response was observed in S. aureus infected femurs, with abundant levels of pro-inflammatory cytokines IL-1α, IL-1β, IL-6, and TNFα detectable as soon as one day after infection, similar to what has been reported in other musculoskeletal infection models." (PMID 30978245, 2019). "Indeed, HRV-infection of BE co-cultured with asthmatic BSM increased the production of pro-inflammatory mediators (IL-1A, IL-6, TNF-alpha) at the transcriptional level compared to that co-cultured with control BSM cells." (PMID 31969885, 2019). "Thus, thrombin activated IL-1α drives two physiological processes in vivo in mice and is generated in humans during generalized infection." (PMID 30926232, 2019). "lncRNA AS1 enhances IL‐1α gene transcription, and disruption of AS‐IL‐1α function can limit IL‐1α transcription and potentially alleviate the damaging effects of excessive IL‐1α levels during infection and inflammatory disease." (PMID 30499165, 2019). "In contrast, IL-1α levels were higher in ΔcnfY mutant-infected ceca during early acute phase, and also the amount of the IL-12p70/IL-23 subunit IL-12p40 was increased during later infection stages compared to wildtype-infected ceca." (PMID 29390040, 2018). "Interestingly, we found more IL-1α secretion (up to 100 ng/mL 48 h post-infection) than IL-1β (590 pg/mL at the same time point)." (PMID 29593716, 2018). "The primary microglia cells experienced a 2.1 pg/mL increase in IL-1α, a 9.72 pg/mL increase in IL-1β, a 35.93 pg/mL increase in IL-6, and a 55.09 pg/mL increase in IL-8 signaling at 2hpi during TC-83 infection." (PMID 30101649, 2018).